DUSP6 (dual specificity phosphatase 6)
Diseases named in the same sentence as DUSP6 in open-access papers (continued):
Sharing a sentence is not in itself a finding about the gene and the disease.
tumor (continued). "Our data therefore indicates that RA-induced upregulation of DUSP6 and RGS16 inhibits tumour cell proliferation, through acting on two levels of RAS-RAF-MEK-ERK signalling pathway and eventually synergistically reducing ERK phosphorylation." (PMID 16012519, 2005). "Our group observed that DUSP6 was overexpressed in primary tumor samples compared to non-tumoral pancreatic tissues by analyzing in silico datasets and spatial transcript profiling." (PMID 41028058, 2025). "Our analysis revealed that DUSP6 was upregulated in primary tumor samples compared to non-tumoral pancreatic tissue across all analyzed datasets." (PMID 41028058, 2025). "In order to explore the expression of DUSP6 in BC tissues, 122 tumor tissues and 34 non-tumor tissues were used for immunohistochemical (IHC) analysis." (PMID 40936711, 2025). "Furthermore, knockdown of DUSP6 in OCT4-overexpressing A549 human NSCLC cells decreased cell migration in vitro and reduced tumor growth and pulmonary metastasis in NOD/SCID mice." (PMID 41210685, 2025). "Future studies should focus on in vivo metastatic models to explore how tumor epithelial cells adapt their metabolism in the absence of DUSP6 to survive and proliferate in secondary niches." (PMID 41028058, 2025). "Moreover, fusion also strongly increased the activity of dual specificity phosphatase 6 (DUSP6)/mitogen-activated protein kinase phosphatase-3 (MKP-3), the key regulators in the p38MAPK pathway, and exogenous overexpression inhibited tumour growth." (PMID 39120301, 2024). "BRAFi-progressed tumours appeared to have reactivated MAPK signalling as DUSP6 expression was not suppressed." (PMID 37563469, 2023). "The antitumor effects were associated with favourable pharmacokinetic properties, as evidenced by the amount of drug exposure in both plasma and tumour, as well as a concordant inhibition of ERK phosphorylation and DUSP6 messenger RNA expression in tumour models." (PMID 37258666, 2023). "The lack of reactivation of ERK phosphorylation in one SR tumour (BoC117) was accompanied with a comparable low rise in DUSP6 expression." (PMID 37604687, 2023). "Among the downregulated genes were DUSP6 (Dual Specificity Phosphatase 6), a key negative regulator of ERK, and ERRFI1 (ERBB Receptor Feedback Inhibitor 1, also called Mig-6), a tumor suppressor that curbs activation of EGFR and sustained signaling through the ERK pathway." (PMID 37020037, 2023). "Considering a subpopulation of NB tumours is maintained by ERK signalling via the ALK oncogene, manipulation of DUSP6 activity might suppress NB cell growth." (PMID 35478300, 2022). "WTAP also upregulated the expression of dual-specificity phosphatase 6 (DUSP6) by stabilizing its mRNA by increasing the m6A modification of its transcript, which induced tumor progression and contributed to WTAP-induced drug resistance via the WTAP/m6A/DUSP6 axis." (PMID 36207306, 2022). "Furthermore, we demonstrated that AZD4547 exhibits an anti-tumor effect on KM12(Luc) by perturbing the TRKA pathway including phosphorylation of PLC-gamma and expression of DUSP6 and ETV1." (PMID 34790577, 2021). "While much is still not understood regarding the role of tumor-produced DUSP6 on tumorigenesis, the function of DUSP6 originating from immune cells is even less well studied." (PMID 30941033, 2019). "No direct evidence of a tumour suppressor function for this MKP has yet been obtained by crossing DUSP6−/− mice into established murine cancer models." (PMID 30401534, 2019).
tumor (continued). "In other words, ERK-dependent tumor cells, including cancers driven by mutant RTK, RAS, BRAF, or MEK proteins, will have a vulnerability to hyperactivated ERK and that vulnerability can potentially be exploited by inhibition of feedback regulators like DUSP6." (PMID 30475204, 2018). "In addition, the proliferation and invasion capacities of tumor cells were significantly down-regulated after overexpressed PP2A and/or DUSP6, compared with control groups." (PMID 28977917, 2017). "Five genes with tumor suppressing properties, i.e. SPRY4 (Sprouty homolog 4), DUSP4 and DUSP6 (dual-specificity phosphatases 4 and 6), LRIG1 (Leucine-rich repeats and Ig-like domains 1) and PHLDA1 (Pleckstrin homology-like domain family A, member 1), were upregulated by KGF (1.5–2.1 fold)." (PMID 22427941, 2012). "Of these, DUSP4 and DUSP6, PHLDA1 and Sprouty 4 are characterized by tumor suppressing properties." (PMID 22427941, 2012). "Moreover, targeting the OCT4-DUSP6 pathway may offer a new therapeutic avenue for NSCLC, as evidenced by reduced tumor growth and lung tumor nodules in mice bearing OCT4-overexpressing A549 lung tumors after silencing DUSP6 expression." (PMID 41210685, 2025). "Notably, we observed that DUSP6 was significantly overexpressed in metastatic samples compared to both primary tumor samples (P < 0.0001) and non-tumorous pancreatic tissue." (PMID 41028058, 2025). "Moreover, in in vivo conditions, the proliferation of subcutaneously implanted A431 xenograft tumor cells lacking DUSP6 was more restricted compared to cells with normal expression of this phosphatase after the action of EGFR inhibitors." (PMID 37760412, 2023). "As ERK activation is known to be required for S-phase entry and cell proliferation, it is possible that the ectopic expression of non-physiological levels of DUSP6/MKP-3 may result in artefactual suppression of tumour cell proliferation and growth." (PMID 26791049, 2016). "In the case of EGFR mutant tumours, DUSP6/MKP-3 loss appears secondary to down regulation of the transcription factor and ERK signalling target Ets1, while the mechanism of DUSP6/MKP-3 down regulation in ELM4–ALK tumour cells was not studied." (PMID 26791049, 2016). "Similarly, we found a positive correlation between DUSP6 and MAPK1 expression in tumor cells, but not in stromal cells, in a human cohort, suggesting that these cells are also dependent on DUSP6 for ERK1/2 modulation; we cannot, however, rule out the involvement of other DUSPs in the process." (PMID 41028058, 2025). "To further confirm the relevance of in vitro DUSP6 knockdown results, we inoculated DUSP6-knockdown or vector control OCT4-overexpressing A549 cells into NOD/SCID mice to investigate whether knockdown of DUSP6 expression could attenuate tumor growth and metastasis in A549/OCT4 tumor-bearing mice." (PMID 41210685, 2025). "Our data suggest that despite a common target in the ERK MAP kinase, DUSP5 and DUSP6 play partially non-redundant roles in suppressing oncogenic KRASG12D signalling, thus retarding both tumour initiation and progression." (PMID 35418690, 2022). "DUSP6 expression is regulated by ERK-signaling and exerts anti-tumor effects via negative feedback regulation in NSCLC." (PMID 25238247, 2014). "In conclusion, the current study has suggested that DUSP6 expression decreases with the depth of invasion in ESCC, predicting tumor progression independent of tumor grade." (PMID 24260056, 2013). "Additionally, there were limited data for the changes from baseline of pharmacodynamic markers in tumor tissue (e.g., phospho-ERK, phospho-AKT, and DUSP6); therefore, these data are not reported, and no definitive conclusions can be made." (PMID 40106536, 2025). "Dual-specificity phosphatase 6 (DUSP6), a specific negative feedback regulator of phosphorylated extracellular signal-regulated kinase, was found to play an important role in numerous types of solid tumors as a tumor suppressor." (PMID 24260056, 2013).
cancer (83 papers, 2011 to 2025). A tumor composed of atypical neoplastic, often pleomorphic cells that invade other tissues. "Especially interesting finding was that the DUSP6 knockdown cells displayed a gene expression pattern linked to dormant cancer cells such as inhibition of MYC, E2F1 targets, and the PI3K/AKT/mTOR signaling, as well as activation of the interferon response." (PMID 38886591, 2024). "DUSP6 gene encodes a protein that counteracts cellular proliferation and is dysregulated in various diseases, including cancer." (PMID 38069001, 2023). "This is in accord with a range of other studies where BCI causes cancer cell cytotoxicity via apparent inhibition of DUSP1 or DUSP6." (PMID 35478300, 2022). "As a member of dual specificity phosphatases subfamily, DUSP6 is tightly linked to malignant progression in various cancers." (PMID 35608100, 2022). "Meanwhile, seven common genes, FOSL1, S100A9, CXCL12, ID2, PRS6KA3, AREG, and DUSP6, have been used as the target biomarkers and even the diagnostic tools in cancer therapy." (PMID 34490085, 2021). "Most studies observed that the expression of DUSP6 was associated with aggressive tumor behavior and malignant phenotypes in many cancers." (PMID 33324561, 2020). "Owing to its uniquely strict specificity toward MAPK1/ERK2 whose activation is involved in oncogenesis, an association between DUSP6 and cancer has been a prime focus of study." (PMID 25699241, 2015). "DUSP6 is also implicated in chemoresistance in several cancers." (PMID 40943262, 2025). "Multiple studies have demonstrated a clear association between DUSP6 and malignant tumor progression; however, its role and underlying mechanisms in BC remain unclear." (PMID 40936711, 2025). "DUSP6 has been implicated in cancer and regulates the MAPK pathway." (PMID 37546772, 2023). "Importantly, nuclear-biased DUSP6 was also present in brain metastases but not pleura or lung metastases in TNBC patients, suggesting that the nuclear DUSP6-associated pathway participates in cancer spreading in TNBC, including brain metastasis." (PMID 31238530, 2019). "However, as is the case for many MKPs much of the mechanistic data obtained so far involves the reversal of cancer-associated phenotypes by ectopic expression of DUSP6/MKP-3 in cancer cell lines and must therefore be treated with a degree of caution." (PMID 30401534, 2019). "Furthermore, DUSP6/MKP-3 is one of a small group of genes that is consistently upregulated in response to elevated ERK signalling in cancer cells harbouring activating mutations in either Ras or Braf, where it is presumed to restrain oncogenic ERK signalling." (PMID 26791049, 2016). "Thus, upregulating DUSP6 or other phosphatases may allow cancer cells to harbor amplification of mutant KRAS alleles." (PMID 36418460, 2022). "Therefore, nuclear DUSP6 may play a role in the association with cancer spreading in TNBC patients, including brain metastasis." (PMID 31238530, 2019). "The hypothesis that DUSP6 regulates ERK activity in the presence of signaling through the RAS pathway is particularly attractive in view of the frequency of RAS gene mutations in human cancers and the difficulties of targeting mutant RAS proteins." (PMID 30475204, 2018). "DUSP6 plays critical roles in development and disease, including an increasing connection to cancer progression." (PMID 40575978, 2025). "We validated this analysis by assessing DUSP6 protein levels in four mouse PDAC cell lines and two mouse cancer-associated fibroblast (CAF) cell lines." (PMID 41028058, 2025).
cancer (continued). "DUSP6 is involved in many physiological functions, including DNA damage repair and stress responses, as well as cancer onset and progression." (PMID 40943262, 2025). "A number of studies have demonstrated a clear role of DUSP6 as an oncosuppressor in different types of cancer, lung cancer being among the most studied." (PMID 40943262, 2025). "Unlike its dual manner functions, pro-oncogenic or tumor-suppressive, in the pathological processes of cancers, the positive function of DUSP6 in white adipocyte adipogenesis is reported." (PMID 40575978, 2025). "This transactivation, facilitated by direct binding of OCT4 to the DUSP6 promoter, is crucial for the growth and migration of cancer cells promoted by OCT4." (PMID 41210685, 2025). "While the expression of DUSP6 in multiple cancer types has been documented, its regulatory mechanisms remain elusive." (PMID 41210685, 2025). "Our study reveals a novel mechanism by which OCT4 promotes the progression of NSCLC through the upregulation of DUSP6, leading to enhanced migratory and invasive capabilities of cancer cells." (PMID 41210685, 2025). "On the whole, DUSP6, one of the most studied DUSPs in cancer, has been shown to have both protumoural and antitumoural properties depending on the type of cancer analysed." (PMID 40943262, 2025). "Previous research has reported that dual-specificity phosphatase 6 (DUSP6), a mitogen-activated protein kinase (MAPK) phosphatase, is associated with cancer cells that display anti-apoptotic, migratory, and drug-resistance phenotypes." (PMID 41210685, 2025). "While demonstrated here for the first time in the context of HER2i therapy resistance, genetic DUSP6 inhibition has recently been shown to inhibit malignant phenotypes in other cancer types." (PMID 38886591, 2024). "DUSP4 and DUSP6 are linked to MAPK signaling in cancers, and in our analysis, DUS4 and DUSP6 both appear on the Volcano and heat map, respectively." (PMID 39768125, 2024). "Mechanistically, DUSP6 inhibition converted cytostatic response to HER2i to an apoptotic response, which is considered as a paramount for cancer therapy strategies aiming for cancer cure." (PMID 38886591, 2024). "On the other hand, RNA-seq data showed that four other genes (DUSP6, NFIX, VIM, and SPARCL1) associated with cancer were also downregulated in CREB5 knockdown cells." (PMID 38418476, 2024). "In short, DUSP6 affects and determines the carcinogenic fate of specific cancers, and is involved in the DNA damage response and regulation of radiosensitivity." (PMID 36982663, 2023). "DUSP6 overexpression was confirmed in a variety of cancer types in both in vitro cells and surgical specimens from patients." (PMID 37760412, 2023). "Their concurrent upregulation was particularly interesting, since a recent report had suggested a digenic dependence on DUSP4 and DUSP6 in MAPK-driven cancers." (PMID 37946160, 2023). "Because low DUSP6 expression occurred more frequently in highly invasive and poorer differentiated cancers, we detected the apoptosis-related proteins in the cell lines overexpressing DUSP6." (PMID 36017891, 2022). "BCI is a small-molecule that acts as a dual-inhibitor of DUSP1 and DUSP6, exerting anti-tumorigenic activity in a wide range of cancer models." (PMID 36589747, 2022). "Taken together, these data corroborate that SKA1 physically interplays with SAFB, which induces SAFB-dependent transrepression of DUSP6, consequently promoting cancer aggressiveness." (PMID 36462498, 2022). "Collectively, our data attest that SKA1 physically interacts with the SAFB and impels transcriptional repression of DUSP6, consequently provoking cancer aggressiveness." (PMID 36462498, 2022). "BCI also demonstrates anti‐tumorigenic activity in a range of cancer models, it is suggested predominantly via inhibition of DUSP6." (PMID 35478300, 2022).
cancer (continued). "Subsequently, seven common genes, including FOSL1, S100A9, CXCL12, ID2, PRS6KA3, AREG, and DUSP6, have been used as the target biomarkers for cancer diagnosis and therapy." (PMID 34490085, 2021). "Although abnormal activation of MAPK signaling is an important factor in cancer progression, DUSP6 influenced stemness by upregulating ALDH1, Nanog, SOX2 and Oct4A and promoted self‐renewal." (PMID 32159851, 2020). "Among the differentially expressed genes, 5 (DUSP6, SOX9, DKK1, ARRDC3 and CSRNP2) were known to be associated with signaling pathways in cancer or cancer stem cells." (PMID 32231719, 2020). "Given the direct involvement of Ras/ERK signalling in human cancer a possible role for DUSP6/MKP-3 has been explored in some depth." (PMID 30401534, 2019). "Among these genes, EGR1, Fos Proto-Oncogene (FOS), FosB Proto-Oncogene (FOSB), Jun Proto-Oncogene (JUN), Dual Specificity Phosphatase 6 (DUSP6) and CTGF have been previously implicated in cancer metastasis." (PMID 30792382, 2019). "Future studies are required to address the precise transcriptional programs underpinning nuclear DUSP6 in cancer spreading in TNBC, especially in brain metastases." (PMID 31238530, 2019). "Overall these findings suggest the potential importance of developing nuclear targeting DUSP6 therapeutics for targeting aggressive TNBC cancer spreading, including brain metastasis." (PMID 31238530, 2019). "BRD9 inhibition by I-BRD9 in Kasumi-1 cells resulted in lower expression of various cancer- associated genes (CLEC1, DUSP6, FES and SAMSN1)." (PMID 28714904, 2017). "At present, there have been many studies of DUSP1 and DUSP6 in cancer, but far fewer studies on the relationship between these proteins and the development of hair follicles." (PMID 28125615, 2017). "The functional role of DUSP5 and DUSP6 was investigated through their silencing in two human BRAFV600E carcinoma cell lines." (PMID 28910386, 2017). "In contrast to findings of other blood-based studies, we found at least four NSCLC-associated markers that were involved in Ras/MAP kinase and cell growth control pathways highly relevant to cancer: DUSP6, GRB2, MDM2, and NF1." (PMID 27418131, 2016). "DUSP1 has been demonstrated to sensitize cancer cells to cisplatin-induced apoptosis and overexpression of DUSP6 in estrogen receptor-positive breast cancer cells confers resistance to tamoxifen." (PMID 25568665, 2014). "In the current study, our preliminary investigation of the DUSP6 downregulation focused on the epigenetic gene silencing, which is important in the initiation and progression of cancer." (PMID 24260056, 2013). "Previous studies have shown that regulating DUSP6 expression is closely linked to cell signalling, particularly the ERK/MAPK pathway, and may modulate the malignant phenotype of cancer cells by affecting cell proliferation and migration." (PMID 39881364, 2025). "The clinical relevance of OCT4 and DUSP6 in cancer recurrence has been documented." (PMID 41210685, 2025). "Several lines of evidence indicate a protumoural role for DUSP6 in other types of cancer." (PMID 40943262, 2025). "The role of DUSP6 in cancer is complex and somewhat contradictory." (PMID 41210685, 2025). "Mitogen-activated protein kinase phosphatase 3 (MKP3), also known as dual-specificity phosphatase 6, is a critical regulator of extracellular signal–regulated kinase (ERK) signaling, and its dysregulation is implicated in diseases, such as cancer." (PMID 40780413, 2025). "Few lines of evidence link DUSP6 to the modulation of ERK5 signalling in cancer cells." (PMID 40943262, 2025). "Importantly, the fusion of MSCs and cancer cells provokes the secretion of the DUSP family dual specificity phosphatase 6 (DUSP6) that can regulate NO production by MAPK kinases and reduce cancer cell survival." (PMID 39120301, 2024).